ACE (angiotensin I converting enzyme)
Diseases named in the same sentence as ACE in open-access papers (continued):
Sharing a sentence is not in itself a finding about the gene and the disease.
Hypertension (continued). "However, the ACE gene DD genotype predisposes to the occurrence of hypertension in the Burkinabe population." (PMID 26351579, 2015). "Activation of the ACE/Ang II/AT1R signaling promotes inflammation, oxidative stress, and fibrosis linked to hypertension, while inhibition of the ACE/Ang II/AT1R signaling has been regarded as important pharmacological tools to prevent and treat vascular diseases such as hypertension." (PMID 25815211, 2015). "This novel finding suggests that hypertension risk, as conferred by ACE I/D polymorphism, may also be modified by the presence or absence of obesity." (PMID 26491214, 2015). "Early detection of DN, adoption of multifactorial interventions targeting the main risk factors (hyperglycaemia, hypertension, dyslipidemia and smoking), and use of agents with a renoprotective effect (ACE inhibitors and/or ARBs) do indeed slow the progression of renal disease." (PMID 28197454, 2014). "Therefore, in order to draw definite conclusions, it is necessary to identify the frequency of ACE gene polymorphism in patients with hypertension and type 2 diabetes mellitus nation-wide." (PMID 25161389, 2014). "Angiotensin-I converting enzyme (ACE) activity has been linked to hypertension." (PMID 25295218, 2014). "On the other hand, ectodomain shedding of ACE has been shown to occur in polarized renal epithelial cells, and N-domain ACE fragments are present in human urine and may associate with hypertension." (PMID 24454948, 2014). "However, among the major risk factors, hypertension characterised 79% of all patients, opportunely treated with medications like ACE inhibitors and beta-blocker, and so forth, during the follow-up and after surgery." (PMID 25120286, 2014). "Interaction between ACE I/D polymorphisms and hypertension exerted an additive effect on CKD risk." (PMID 24498151, 2014). "In a large prospective cohort of patients (the SMART-MR study) with symptomatic atherosclerotic disease, elevated serum ACE activity was associated with increased risk of ischemic stroke and high blood pressure and increased progression of white matter ischemic damage." (PMID 25309424, 2014). "The M235T variant of the AGT is significantly associated with female hypertensives and ACE DD variant could be a risk allele for essential hypertension in south India." (PMID 24860821, 2014). "The differences in the two domain functions may in part explain why tag-SNPs in LD block 3 have slightly higher association with ACE activity and tag-SNPs in LD block 2 have higher association with young-onset hypertension." (PMID 23469169, 2013). "The data obtained in our report supports to the hypothesis that ACE activity and hypertension are associated." (PMID 24098401, 2013). "In the present study, A allele of rs4305 increases the susceptibility to hypertension, which might be associated with increased ACE activity." (PMID 24015270, 2013). "The deletion/insertion (D/I) polymorphism in intron 16 of the gene encoding angiotensin converting enzyme (ACE) on chromosome 17q23 has been associated with several cardiovascular disorders including LVH in untreated hypertension, complications of atherosclerosis, and HCM." (PMID 24204726, 2013). "However, findings associating ACE insertion/deletion polymorphism with hypertension or other related traits are inconsistent." (PMID 23469169, 2013). "In addition, ACE activity was both significantly associated with ACE I/D polymorphism and hypertension." (PMID 24098401, 2013). "Further research is needed to examine whether the association between rs1800764 and hypertension occurs via elevated ACE activity or via another kidney mechanism." (PMID 23469169, 2013). "The additive model (ID, DD versus II) of the ACE (rs4646994) genotype revealed an association with hypertension with adjusted OR of 1.43(95% CI: 1.04-1.97), and ID genotype with adjusted OR of 1.72(95% CI: 1.01-2.92), DD genotype with adjusted OR of 1.94(95% CI: 1.01-3.73), respectively." (PMID 24098401, 2013).
Hypertension (continued). "Similarly, the inhibition of Angiotensin-1 converting enzyme (ACE) activity is a modern therapeutic approach in the management of hypertension which is one of the complications associated with type-2 diabetes." (PMID 24348547, 2013). "However, the evidence of the potential role of the I/D polymorphism to diferential ACE expression for the development of human hypertension was weak." (PMID 24098401, 2013). "However, the ACE polymorphism has a role in lacunar infarction that is independent from hypertension." (PMID 23480670, 2013). "Patients with hypertension using ACE inhibitors have a significantly lower risk of headache." (PMID 23773858, 2013). "ACE activity and risk of acquiring young-onset hypertension among people with different genotypes." (PMID 23469169, 2013). "The main weapon in the treatment of hypertension represents, as is natural, mineralocorticoid receptor antagonists, generally associated with other classes of antihypertensive agents (ACE inhibitors, angiotensin receptor blockers, Ca blockers, α-or β- blockers)." (PMID 23049641, 2012). "ACE (angiotensin-converting enzyme) is associated with hypertension." (PMID 24957872, 2011). "Recent data suggest that the Renin Angiotensin System might be involved in the pathophysiology of obesity and associated hypertension; therefore, ACE gene might be a good candidate for MetS." (PMID 22168210, 2011). "By contrast, a meta-analysis including data on 11,000 Han Chinese found the ACE DD genotype to be associated with higher risk of hypertension when compared to the ACE II genotype (OR[95%CI] = 1.61 [1.32-1.96]), but there was a high degree of heterogeneity across studies." (PMID 23049672, 2011). "However, on the other hand, a significant association of the ACE D allele with hypertension in African Americans, Chinese and Japanese population has already been established." (PMID 28352369, 2010). "The pharmacological treatment for control of hypertension utilizes various drug therapies, single doses or associations of diuretics, beta-blockers, calcium channel blockers, angiotensin converting enzyme (ACE) inhibitors and angiotensin II receptor (AT1) antagonist (ARA)." (PMID 20657427, 2010). "The ACE I/D genotype is positively associated with hypertension in our population." (PMID 28352369, 2010). "Furthermore, the hazard ratio of ACE DI genotype in hypertensive cases was found to be 1.08 times and of ACE II genotype 1.90 times that of general control population, indicating thereby that ACE I allele is associated with the increased risk of hypertension." (PMID 28352369, 2010). "Therefore, we carried out a case-control study in our population to determine if this ACE I/D polymorphism is associated with an altered risk of hypertension in our population." (PMID 28352369, 2010). "The heterogeneity in association of ACE I/D polymorphism with essential hypertension may be either due to varied ethnicity or the various other genetic and environmental factors implicated in the regulation of blood pressure." (PMID 28352369, 2010). "A recent case-control study found that subjects with the ACE DD genotype were 1.6 times more likely to be hypertensive than carriers of the I allele, and that 15% of all cases of hypertension could be attributed to the ACE DD genotype." (PMID 19291311, 2009). "Given the importance of the renin-angiotensin system in long-term blood pressure regulation, further characterisation of the genetic determinants of circulating ACE has the potential to improve our understanding of the mechanisms underlying the development of high blood pressure." (PMID 18544166, 2008). "Several studies such as RALES, EPHESUS, 4E and others, recently showed that mineralocorticoid-receptor (MR) antagonists, alone or in combination with ACE inhibitors or ARBs, reduced the risk of progressive target organ damage and hospitalization in patients with hypertension and heart failure." (PMID 16604252, 2006).
Hypertension (continued). "As to the association of antihypertensive drugs, 24 cases (33.3%) and 11 controls (23.9%) used more than one anti-hypertension drug, which prevailed among cases - 6 individuals (8.3%) and among the controls - 5 individuals (10.8%), with association of diuretic agents plus ACE inhibitors." (PMID 17143434, 2006). "Given that the genetic instrument used for ACE levels was associated with lower systolic blood pressure, people with these variants may be less likely to develop hypertension and subsequently less likely to be prescribed and treated with pharmacological ACE inhibitors." (PMID 41085561, 2026). "Additionally, the fact that higher ACE/ACE2 ratios have been linked to hypertension and worse outcomes in Covid-19 could implicate MARCO in the susceptibility to severe disease." (PMID 41439503, 2025). "Additionally, animal and in vitro studies have demonstrated antihypertensive and ACE-inhibitory properties of soy peptides, which may improve vascular function and indirectly support brain health, given the link between hypertension and dementia risk." (PMID 41010462, 2025). "The effect of MEG3 gene variations on the susceptibility to DN could be another instance of genotype-gender interactions in human diseases, just as observations on variants of RELN gene with schizophrenia 46 and polymorphic alleles of ACE gene with hypertension." (PMID 40765563, 2025). "Additionally, the fact that higher ACE/ACE2 ratios have been linked to hypertension and worse outcomes in Covid-19 30 could implicate MARCO in the susceptibility to severe disease." (PMID 40093086, 2025). "Consequently, ACE inhibitors, α and β receptor blockers, and angiotensin II receptor antagonists contribute to maintaining normal blood pressure and decreasing the risk for hypertension and cardiovascular disease." (PMID 39452081, 2024). "2.In ethnic groups with high ACE activity, the association between different ACE I/D genotypes and blood pressure levels is erased; however, these groups are generally more susceptible to developing hypertension than the low ACE activity population in which the ACE DD variant becomes a risk factor." (PMID 38707445, 2024). "However, it’s important to acknowledge that synthetic DPP-IV and ACE inhibitors have specific adverse effects, prompting researchers to explore natural alternatives; diabetes and hypertension are the two most prevalent risk factors for atherosclerosis and cardiovascular disease." (PMID 38575133, 2024). "Furthermore, prevention of over-activation of RAAS, as implicated by the lower expression level of ACE, could also have contributed to the observed amelioration of hypertension." (PMID 39057713, 2024). "Additionally, antihypertensive medication, like ACE-inhibitors, were shown to have immunomodulating properties, which also might contribute to the observed association between hypertension and post-COVID-19-vaccination S1RBD IgG responses." (PMID 39204074, 2024). "There are many factors associated with the development of hypertension, one of them is related to the conversion of angiotensin I, an active decapeptide, into angiotensin II, a potent vasoconstrictor octapeptide, by the angiotensin-converting enzyme (ACE) system." (PMID 37284652, 2023). "Thus, ACE inhibition controlled and reduced the risk of hypertension." (PMID 37050065, 2023). "Moreover, ACE inhibitors and angiotensin II receptor blockers may reduce levodopa-induced dyskinesia occurrence in PD patients with hypertension, and the use of ACE inhibitors has been linked to a reduced number of falls in these patients." (PMID 36836893, 2023). "Interestingly, the use of ACE inhibitors and angiotensin II receptor blockers has been associated with a potential protective effect on the cognitive impairment of PD patients with hypertension." (PMID 36836893, 2023).
Hypertension (continued). "Regarding blood pressure, rats with taurine deficiency contracted more severe hypertension than their control counterparts, and elevated blood pressure could be reduced by taurine treatment, potentially through modulating angiotensin-converting enzyme (ACE) activity and nitric oxide (NO) synthesis." (PMID 37571314, 2023). "Therefore, this study aimed to assess the effect of ACE gene insertion/deletion (I/D) polymorphism on anthropometric and biochemical parameters among essential hypertension patients at the University of Gondar Comprehensive Specialized Hospital, Northwest Ethiopia." (PMID 37200278, 2023). "Interestingly, high blood pressure was also associated with the ACE D/D genotype in obese youths." (PMID 37238156, 2023). "Thus, our results might contribute toward incorporating ACE inhibitory peptides in functional foods or drug formulations for the therapy of diseases associated with hypertension." (PMID 36825069, 2022). "ACE inhibitory peptide has remarkable effects in alternative drugs for treating hypertension, but it is usually necessary to take antihypertensive drugs for life, and further clinical trials are needed to determine whether ACE inhibitory peptide will increase the risk of cancer." (PMID 35923206, 2022). "This substantial association of the DD genotype and the D allele with increased risk of hypertension could be attributed to the deletion of a 287-bp non-coding region in the 16th intron of the ACE gene, which would result in increased ACE gene transcription and ACE activity." (PMID 36355860, 2022). "People with hypertension or cardiovascular disease have a higher risk of COVID-19 infection and severe COVID-19 course potentially be associated with the use of angiotensin-converting enzyme (ACE) inhibitors and angiotensin receptor blockers (ARBs) for treatments." (PMID 36293576, 2022). "Therefore, the present study aimed to determine the association of ACE gene I/D polymorphism with the risk of hypertension among hypertensive patients with their corresponding control groups at the University of Gondar Comprehensive Specialized Hospital, Gondar, Ethiopia." (PMID 36355860, 2022). "Moreover, this study corroborated the usefulness of brewing peptides to reduce the risk, ameliorate, or treat primary hypertension since the final products presented similar or higher ACE-inhibitory capacity than captopril, a clinically used antihypertensive drug." (PMID 36294989, 2022). "One ailment that seaweed bioactive compounds may impact is hypertension caused by the enzyme Angiotensin Converting Enzyme 1 (ACE-1; EC 3.4.15.1), found within the Renin-Angiotensin Aldosterone System (RAAS), which causes vasoconstriction of blood vessels, including veins and arteries." (PMID 35741988, 2022). "The ACE DD genotype may be a susceptible genotype for essential hypertension." (PMID 35130889, 2022). "However, it is unclear whether ACE-2-stimulating drugs or the complication itself increased risk of death for hypertension and diabetes." (PMID 33857224, 2021). "The researchers found that delphinidin's anti-diabetes mechanism with hypertension may be associated with its strong antioxidant activity, inhibiting α-glucossidase and α-amylase, angiotensin converting ase (ACE) and direct vascular relaxation or calcium channel regulation." (PMID 34692849, 2021). "However, consistent with the known pharmacological effect of ACE inhibitors to lower blood pressure, increased ACE expression colocalised with increased hypertension risk which might limit exploration of this target to treat or prevent Alzheimer’s disease." (PMID 33417599, 2021). "The 2017 American College of Cardiology (ACC)/American Heart Association (AHA) hypertension guidelines recommend four classes of agents as first-line therapy for managing essential hypertension, and among them are angiotensin-converting enzyme (ACE) inhibitors." (PMID 34567875, 2021).
Hypertension (continued). "Thus, rs4341 and rs4343 polymorphisms of ACE could be predictive markers of severity of COVID-19 in those patients with hypertension, dyslipidemia or diabetes." (PMID 34489863, 2021). "Finally, although in the preliminary stages of the study, ACE deletion genotype was more significantly correlated to an increase in childhood adiposity, elevated adult diastolic blood pressure, and a higher risk of hypertension." (PMID 34912641, 2021). "Some studies have reported an association of the GG genotype of rs4343 polymorphism and higher circulating levels and activity of ACE, which could explain the higher susceptibility to develop severe forms of the disease in patients with the GG genotype, in addition to hypertension and dyslipidemia." (PMID 34489863, 2021). "Also, ACE I/I and D/D genotypes were more frequent in the hypertensive patients compared to a control healthy group emphasizing the significant association between ACE gene polymorphisms and early-onset essential hypertension in people less than 40 years old." (PMID 33907634, 2021). "However, other experimental evidence has shown a protective effect of RAAS inhibition in COVID‐19 patients, and, in a recent retrospective clinical study, the use of ACE inhibitors and ARBs was associated with lower overall mortality among hospitalised COVID‐19 patients with hypertension." (PMID 32364264, 2020). "SRC is characterized by severe hypertension, followed by glomerulosclerosis, which ends with acute or chronic renal dysfunction, but it no longer represents one of the main complications associated with SSc, thanks to angiotensin converting enzyme (ACE)-inhibitor treatment." (PMID 31487964, 2019). "Following prenatal inflammatory stimulation, early life and adult lifelong NF-κB activation ignites the NF-κB → ACE → Ang II → NF-κB positive feedback loop in conduit artery, which in turn predisposes to aortic dysfunction and development of prenatal inflammation programmed hypertension." (PMID 26877256, 2016). "Additionally, associations between the ACE gene I/D polymorphism and hypertension were analyzed." (PMID 28115791, 2016). "Hence, we hypothesized that genetic associations of the ACE gene with T2DM or hypertension may depend on the obesity status." (PMID 26491214, 2015). "In conclusion, through a well-designed Mendelian randomization meta-analysis, our findings demonstrate that ACE gene I/D polymorphism can predict the risk for OSAS complicated with hypertension, and more importantly, genetically-reduced serum ACE activity might be a causal risk factor for OSAS." (PMID 26486181, 2015). "However, it is difficult to say that this polymorphism is a definite risk factor for RVO, due to the scarcity of large-scale studies evaluating the distribution of ACE I/D gene polymorphism in patients with diabetes mellitus and/or hypertension among Turkish population." (PMID 25161389, 2014). "It was proposed that the differences in ACE expression related to ACE I/D polymorphism may play a role in the occurrence of myocardial infarction, coronary artery disease, coronary artery calcification, heart failure and hypertension." (PMID 24690767, 2014). "However, the association obtained between RVO and ACE I/D gene polymorphism might be due to the association between ACE I/D gene polymorphism and diabetes mellitus and/or hypertension." (PMID 25161389, 2014). "Therefore, in order to identify ACE I/D gene polymorphism as a predictor for RVO, ACE allele frequency in healthy individuals and ACE gene polymorphism frequency in patients with essential hypertension and type 2 diabetes mellitus should be considered in the population studied." (PMID 25161389, 2014). "Because we have identified functional ACE polymorphisms for hypertension in regions several kb upstream of the I/D polymorphism, this may in part explain why consistent associations between I/D polymorphism and blood pressure/hypertension are lacking in the literature." (PMID 23469169, 2013).